KLF5 (KLF transcription factor 5)
Diseases named in the same sentence as KLF5 in open-access papers (continued):
Sharing a sentence is not in itself a finding about the gene and the disease.
tumor (continued). "KLF5 acts as a fundamental core regulator of intestinal oncogenesis at the stem-cell level, enhancing the nuclear localization and transcriptional activity of β-catenin, aiding tumor initiation, which is the target for a variety of antitumor drugs." (PMID 36761967, 2023). "Similarly, KLF5, known and best described as an oncogene under specific circumstances, also has tumor-suppressive functions." (PMID 37173904, 2023). "While exogenous KLF5 rescued the expression level in PRMT5‐deficient cells, the absence of PRMT5‐dependent KLF5 limited its ability to promote tumour growth." (PMID 37461162, 2023). "Univariate analysis revealed that KLF5 protein levels were related to the tumor residual margin (p = 0.031) and diaphragm metastasis (p = 0.038), and multivariate analysis confirmed a correlation between KLF5 expression and tumor residual margins (p = 0.014)." (PMID 37702443, 2023). "Notably, the combination of suberoylanilide hydroxamic acid (SAHA) and olaparib significantly inhibits tumor growth and metastasis of PARPi‐resistant OC cells with high KLF5." (PMID 37702443, 2023). "Furthermore, an anti-Cd8 neutralizing antibody was applied to block Cd8+ T cells in the EMT6 mouse model, indicating that Cd8+ T-cell depletion facilitated tumor growth in both the control and Klf5 KD groups." (PMID 36923542, 2023). "Tumor development involves a dedifferentiation process which occurs with ectopic re-expression of stemness genes like Octamer-4 (Oct4), Nanog, Kruppel-like factor 4 (Klf4) or Kruppel-like factor 5 (Klf5)." (PMID 38137514, 2023). "Although evidence has demonstrated the critical functions of KLF5 in pathological processes of tumor progression, whether KLF5 is a tumor suppressor or oncogene is still debatable." (PMID 38087142, 2023). "Additionally, Klf5/Cox2 axis activation reduced the number of tumor-infiltrating CD8+ T cells, and CEL partially increased CD8+ T cell infiltration." (PMID 36923542, 2023). "The protective effect of KLF5 on Th17-mediated immune response may lead to the immune escape of tumor tissues, as Th17 can recruit immune cells, secret the antitumor factor IFN-γ and is an essential mediator of adoptive immunotherapy." (PMID 36761967, 2023). "Conversely, other studies describe KLF5 as a tumor suppressor." (PMID 38087142, 2023). "The results showed that KLF5 knockdown significantly reduced the tumor size of OC cells." (PMID 37702443, 2023). "Knockdown of KLF5 significantly attenuates triple-negative breast cancer tumor growth." (PMID 38087142, 2023). "Given that the KLF5 transcription factor promotes tumor proliferation, invasion and stemness in diverse cancers 9, its role in antitumor immunity remains largely unknown." (PMID 36923542, 2023). "Overexpression of KLF5 may be used as a predictive biomarker for poor tumor regression after preoperative chemoradiation therapy, the standard treatment for locally advanced rectal cancer." (PMID 37173904, 2023). "KLF4 and KLF5 were downregulated and played tumor suppressor roles in RCC." (PMID 35787628, 2022). "Sixty FDA-approved anti-tumor drugs and small molecule compounds were used to conduct drug screening assays, and the results showed that compared with monotherapy, the KLF5 inhibitor ML264 significantly increased oxaliplatin sensitivity in oxaliplatin-resistant PDOs." (PMID 35379798, 2022). "In most other tumor types, both KLF5 amplification and deletion were observed." (PMID 33923166, 2021). "Therefore, in the hypoxic tumor microenvironment, genes that are involved in mechanisms related to stemness and drug resistance, such as Tie1 and KLF5, are artificially upregulated." (PMID 33461544, 2021). "Furthermore, the inhibition of KLF5 markedly decreased MMP-2, MMP-9 and VEGF, which further confirms the role of KLF5 not only in tumor growth, but also in migration and angiogenesis and overall metastatic potential of PTC cells." (PMID 33430300, 2021). "The tumor-inhibiting properties of KLF5 knockdown were substantiated in vivo." (PMID 34548487, 2021).
tumor (continued). "The expression of E2F2 and KLF5 was more prominent at the edge of the tumor cystic wall." (PMID 35155179, 2021). "Therefore, Ac-KLF5 also appears to be required for tumor cells in the bone to maintain a mesenchymal phenotype." (PMID 33731701, 2021). "There were data revealing that KLF5 commonly remains inactivated during carcinogenesis in humans and hence could be a tumour inhibitor gene, and several functional investigations actually back up a tumour inhibitory role of KLF5." (PMID 34799978, 2021). "Therefore, the tumor-supporting properties of KLF5 in GC were achieved through activating DANCR transcription." (PMID 34548487, 2021). "Our study suggests that LINC00152 promotes tumor progression by interacting with KLF5." (PMID 33842324, 2021). "Therefore, we wanted to investigate the effect of pharmacological inhibition of KLF5 on PTC tumor growth in vivo." (PMID 33430300, 2021). "Therefore, acetylation of KLF5 in tumor cells is indeed required for inducing osteoclast differentiation." (PMID 33731701, 2021). "Taken together with the reports that IL-11 binds to its receptors on osteoclasts or their precursors to regulate the formation and function of osteoclasts, these findings suggest that the Ac-KLF5/CXCR4 axis in tumor cells induces osteoclast differentiation by increasing IL-11 secretion." (PMID 33731701, 2021). "Although validation using TCGA cohort showed higher KLF5 expression was associated with better survival, it was not an independent prognostic factor when considering confounding factors, including tumor stage and molecular classification." (PMID 33923166, 2021). "GEPIA program displayed that KLF5 was highly expressed LUSC tumor tissues." (PMID 33931086, 2021). "Induction of osteoclastogenesis by Ac-KLF5-expressing tumor cells also indicates that Ac-KLF5 activates paracrine signaling in tumor cells to mediate tumor cells’ interaction with osteoclasts or osteoblasts, which also provides a mechanism for how Ac-KLF5 causes bone metastatic lesions." (PMID 33731701, 2021). "In this study, we reveal that KLF5 is highly expressed in 65.1% of PTC tumor samples (793/1219)." (PMID 33430300, 2021). "Interestingly, using VIPER-D, there was only moderate correlation with SCIRA’s predictions, with VIPER-D not predicting preferential inactivation and failing to predict inactivity of established tumor suppressors such as KLF5 and CDX1." (PMID 33083012, 2020). "The role of KLF5 in androgen-induced cell proliferation and tumor growth could also involve KLF5′s function in tumor microenvironment (TME) and immune responses." (PMID 32245249, 2020). "KLF5 might inhibit cell invasion by suppressing the transcription of IGF1 in tumor cells and subsequently inhibiting its downstream activation of STAT3/MMP9." (PMID 32546700, 2020). "Indeed, KLF5’s E419Qmutation has recently been experimentally shown to change wild-type binding preferences and increase the expression of tumor progression genes in vivo." (PMID 32711844, 2020). "We demonstrated that silencing KLF5 inhibited cell proliferation and tumor growth of PCa cells." (PMID 32245249, 2020). "In summary, we demonstrated that KLF5 is crucial for androgen/AR signaling to activate the transcription of specific genes, including some that mediate cell proliferation, and to promote cell proliferation and tumor growth in PCa cells." (PMID 32245249, 2020). "Considering that paracrine TGF-β is present in the tumor microenvironment, the finding from the xenograft mouse model further supports a critical role of acetylated KLF5 in DTX resistance, which thus suggests acetylated KLF5 as an alternative target of TGF-β's tumor promoter function." (PMID 32685011, 2020). "KLF5 is considered a tumor suppressor in PCa as it is frequently deleted or downregulated." (PMID 32546700, 2020).
tumor (continued). "In addition, KLF5 has been reported as an oncogene that suppresses cancer cell growth and is involved in tumor progression in CRC mouse models." (PMID 31336886, 2019). "Moreover, both overall and tumor-free survival were shorter in patients exhibiting high KLF5 expression." (PMID 31327760, 2019). "KLF5 is a hormone-regulated gene in PCa and may have an oncogenic or tumor suppressive role depending on posttranscriptional modifications." (PMID 31903168, 2019). "Krueppel-like factor 5 (KLF5) acts as a tumor inhibitor in some cancer types." (PMID 31640265, 2019). "The current study also provides novel information about the signaling pathways associated with TTK overexpression and tumor aggressiveness in TNBC, including its interaction with TGF-β signaling and its regulation of the EMT regulators KLF5, miR-21, and miR-200s." (PMID 30206215, 2018). "Ectopic over-expression of KLF5 only partially rescued MIT’s anti-tumor activity in HCC1806." (PMID 29348684, 2018). "Although these results may be significant, they are rather generalised and further study is needed to confirm the expression of KLF5 and TNFRSF11a mRNA and protein in clinical CC tumours." (PMID 29146991, 2017). "In our study, KLF5 functions as a tumor suppressor in ccRCC." (PMID 28749461, 2017). "Transcription factor Krüppel-like factor 5 (KLF5) exerts diverse functions in various tumor types." (PMID 28749461, 2017). "Given that ectopic KLF5 expression inhibited ccRCC cell growth in vitro, whether KLF5 also affected tumor growth in vivo was further investigated." (PMID 28749461, 2017). "In addition, The LPA-LPA2 signaling axis promotes tumor cell proliferation through the activation of transcriptional factors, such as β-catenin, Kruppel-like factor 5 (KLF5), NF-κB, and hypoxia-inducible factor 1α (HIF-1α)." (PMID 27124742, 2016). "It is clear that KLF5 knockdown inhibits tumour growth much more than BAP1 knockdown in this model." (PMID 26419610, 2015). "In addition, the functions of BAP1 and KLF5 are similar in terms of promoting cell cycle progression, migration, tumour growth and lung metastasis." (PMID 26419610, 2015). "Also, initial studies revealed KLF5 to be a potential tumor suppressor gene in BC, however, a recent study found that patients with a higher KLF5 expression have shorter disease-free and OS than patients with a lower KLF5 expression." (PMID 25897424, 2015). "On one hand, its genetic locus is frequently deleted in human cancers; a tumor suppressor function has been established in mouse models where KLF5 expression suppresses tumor growth and deletion of Klf5 in mouse prostates promotes tumorigenesis initiated by the deletion of Pten." (PMID 25896712, 2015). "However, levels of Klf5 and Tgif1 were elevated in R482Q/+;1322T compared with 1322T tumours (p=0.045 and p=0.042, respectively, t test), consonant with the findings in normal intestinal epithelium." (PMID 23676439, 2014). "Therefore, KLF5 was proposed to be a tumor suppressor gene, even though it can transform fibroblasts and promote the proliferation of epithelial cells and tumorigenesis of some cancer cell lines." (PMID 23755247, 2013). "In addition, quantification of total tumor Vegf, Klf5 and Oct4 transcript levels indicated that Egln3H196A induction did not inhibit Hif-mediated transcription whereas tumors expressing wild-type Egln3 displayed decreases in Vegf, Klf5 and Oct4 in vivo." (PMID 22905089, 2012). "This increase in tumor number was reduced by 92% in triple transgenic ApcMin/KRASV12/Klf5+/- mice." (PMID 20298593, 2010). "Klf5 haploinsufficiency in ApcMin mice resulted in a significant decrease in tumor number and size." (PMID 20298593, 2010). "We recently reported the critical role for Klf5 in tumor initiation in ApcMin mice." (PMID 20298593, 2010). "Klf5 can also function as either a tumour suppressor or an oncogene." (PMID 20514221, 2009).
tumor (continued). "Emerging evidence exhibits that CDC4 has been confirmed as a tumour suppressor due to the wide involvements in degradation of diverse proteins associated with oncogenic developments, including cyclin E, c-Myc, c-Myb, c-Jun, Notch, MCL1, MED13/13L, PGC-1α, C/EBPα, TGIF1 and KLF5." (PMID 40260685, 2025). "However, there are certain requirements for inclusion in clinical patients, for example, tumor tissue samples should have increased protein expression of KLF5, XPO1 and Cyclin D1, and no mutation of RB1 and positive expression in the cytoplasm." (PMID 39888288, 2025). "A previous study displayed that KLF5 knockdown elevated the number and functionality of intratumoral antitumor T cells, suggesting that KLF5 may have immunosuppressive effects to contribute to tumor cell immune escape." (PMID 39720765, 2025). "Here, we report that PTEN deficiency induced Krüppel-like factor 5 (KLF5) acetylation and that interruption of KLF5 acetylation orchestrated intricate interactions between cancer cells and CAFs that enhance FGF receptor 1 (FGFR1) signaling and promote tumor growth." (PMID 38781024, 2024). "Moreover, diverse clonal populations within ESCC tumours and how this diversity might affect the sensitivity of tumour cells to NEDD4L/KLF5 axis inhibition." (PMID 39317954, 2024). "Thus, tumor-intrinsic Klf5 expression may contribute to the alteration of overall immune compositions in the TME by mediating the proliferation, differentiation, chemotaxis and activation of T cells." (PMID 36923542, 2023). "Notably, KLF5 is a key transcription factor that maintains tumor stemness 9, suggesting that KLF5 may impair antitumor immunity through the sustainability of neoplastic stemness." (PMID 36923542, 2023). "However, in tumor tissues, acetylated KLF5 was detrimental to the growth of CSCs-rich cell lines." (PMID 36761967, 2023). "Accumulating evidence has shown that KLF5 may remodel the tumor microenvironment." (PMID 36923542, 2023). "Finally, the depletion of KLF5 regressed PTC tumor growth in nude mice." (PMID 33430300, 2021). "A previous study has revealed, in a small number of PTC tumor samples, an association between KLF5 and lymphnode metastasis, but not other clinical parameters, which could be due to the small number of patient samples in their cohort." (PMID 33430300, 2021). "Notably, the 177 patients in the TCGA dataset could be clearly better and poorer tumor-free survival groups based on the KLF5 expression level." (PMID 31327760, 2019). "This led to the identification of 30 miRNA-mRNA interaction pairs involving known tumor suppressor targets of miR-21a-5p (Reck, Timp3 and Tgbr3) and miR-31-5p (Lats2 and Dmd) as well as oncogenic targets of miR-143-3p (Kras), miR-145-5p (Klf5, Kras) and miR-1195-5p (Met)." (PMID 30412601, 2018). "Herein, we report that BCR-ABL1+ B-ALL has a strikingly reduced expression of KLF5, which is supported by the reported hypermethylation of the KLF5 promoter in patient-derived BCR-ABL1+ leukemic cells, suggesting that KLF5 may play preferentially a role as tumor suppressor in BCR-ABL1+ B-ALL." (PMID 30038712, 2018). "Thus, KLF5’s function as an oncogene or a tumor suppressor may depend on the types and stages of tumors." (PMID 29898734, 2018). "These analyses indicated that KLF5 might be a tumor suppressor in ccRCC." (PMID 28749461, 2017). "Indeed, all 5637/shKLF5 xenograft tumors were pale and almost no blood vessels were shown on the surface of tumor capsule, indicating a deficient angiogenesis after KLF5 knockdown." (PMID 26544730, 2015). "Therefore, we suppose that other effects (such as cell-cell interaction in tumor microenvironment) may play a critical role in the modulation of in vivo tumor growth by KLF5 beyond regulating autonomous cancer cell proliferation." (PMID 26544730, 2015).
tumor (continued). "In addition, knockout of Klf5 in prostate epithelial cells, mediated by probasin promoter-driven Cre expression, did not cause neoplasia but promoted cell proliferation and induced hyperplasia when one Klf5 allele was knocked out." (PMID 23755247, 2013). "The effects of the KLF5 inhibitor ML264 were tested in vitro using cell viability and apoptosis assays, and in vivo using a xenograft mouse model to evaluate tumor growth and response to PARPi treatment." (PMID 40307891, 2025). "The study revealed that KLF5 deletion significantly slowed tumor growth and increased intratumoral CD8+ T cell infiltration, indicating that KLF5 promoted tumor progression by suppressing CD8+ T cell infiltration." (PMID 40867511, 2025). "Several tumor-specific TFs were detected within the ED and SED, including TP63, FOSL1, JUND, GRHL2, SNAI2, KLF5, TP73, and SMAD3." (PMID 41323280, 2025). "We found that KLF5 was elevated in PDAC tumors and metastases relative to normal pancreas tissue, with similar levels in both classical and basal-like tumor subsets." (PMID 41241675, 2025). "The analyses identify 3,447 tumor‐specific oncogenic enhancers (SOEs) enriched for master transcription factors (SOX2, TP63, KLF5, GRHL2) that orchestrate malignant programs." (PMID 40899632, 2025). "applied 10X Visium on 4 TNBC samples, showing that KLF5 expression co‐localised with basal markers (KRT5, KRT14, KRT17) in tumour regions, while areas with reduced KLF5 expression were enriched with CD4+ and CD8+ T cells." (PMID 40677104, 2025). "In contrast, the ED analysis revealed 204 TFs, with 30 showing substantial tumor-specific TFBS enrichment, including TP63, FOSL1, JUND, JUNB, and KLF5, underscoring their potential roles in tumorigenesis." (PMID 41323280, 2025). "The KDM3A/KLF5/SMAD4/EGFR axis coordinates the regulatory mechanism involved in maintaining a low population of T cells within the tumor microenvironment (TME), thus driving resistance to immunotherapies." (PMID 39519018, 2024). "We further investigated the proliferation, invasion and migration of ESCC cells and observed tumour growth in vivo after modulating NEDD4L and KLF5." (PMID 39317954, 2024). "The acetylation of KLF5 bolsters CXCR4 expression and interleukin‐11 secretion, fueling osteoclast differentiation and tumor cell plasticity in PCa bone metastasis." (PMID 38374872, 2024). "In contrast, CsA alone or combined with CB-839 have minor effects on NRF2, KLF5, and SLC1A5 proteins derived from WT-201 tumor samples." (PMID 38830868, 2024). "Ablation of KDM3A, KLF5, SMAD4, or EGFR elevates the population of tumor-infiltrating T cells and dendritic cells and decreases myeloid cell infiltration." (PMID 39519018, 2024). "Meanwhile, tumour weight was elevated after NEDD4L silencing and significantly reduced after KLF5 inhibition." (PMID 39317954, 2024). "Our previous studies demonstrated that TNFAIP2 is a KLF5 downstream target gene in response to TNFα and TNFAIP2 knockdown inhibited HCC1806 xenograft tumor growth." (PMID 39532855, 2024). "KLF1, KLF5, and KLF8 promote tumor proliferation by activating the expression of the WNT/β-catenin pathway." (PMID 36761967, 2023). "Given the functions of KLF5 in the tumor-immune microenvironment (TIME), knowing the mechanisms by which KLF5 influences the composition of the TIME is crucial." (PMID 36923542, 2023). "To verify this function, we constructed an olaparib‐resistant PDX mouse model with KLF5 high expression and found that olaparib combined with SAHA significantly inhibited subcutaneous tumor formation compared to SAHA or olaparib treatment." (PMID 37702443, 2023). "On the one hand, the KLF5 locus at chromosome 13 is frequently deleted in human BC, and its protein is degraded by the WWP1 oncogenic ubiquitin E3 ligase, which suggests a tumour-suppressor function." (PMID 36765262, 2023). "PET‐CT showed that KLF5 knockdown in OC cells reduced SUV uptake and the number of abdominal tumor nodules." (PMID 37702443, 2023).